AR (androgen receptor)
Diseases named in the same sentence as AR in open-access papers (continued):
Sharing a sentence is not in itself a finding about the gene and the disease.
prostate carcinoma (continued). "This structural study provides additional evidence and mechanistic insight into CHD1’s roles in modulating AR signaling and ERG fusions during prostate cancer evolution." (PMID 36776288, 2023). "In early prostate cancer, Rb tightly regulates E2F1, which in addition to acting on CycE, also controls the expression levels of AR, therefore linking Rb/E2F and AR signalling." (PMID 37363926, 2023). "In multiple prostate cancer cell lines, PARP7 can be induced by treating cells with agonists for AR and AHR." (PMID 37077937, 2023). "Recently, the development of selective androgen receptor modulators, the great effect of AR–related therapy in prostate cancer and the in-depth study of luminal androgen receptor (LAR) subtype of breast cancer have highlighted AR." (PMID 36929229, 2023). "Another bioassay has been developed to screen for molecules interacting with LNCaP cells, which is an androgen receptor (AR)-positive and prostate-specific antigen (PSA)-expressing prostate cancer cell line." (PMID 36765659, 2023). "Prostate cancer initially responds to androgen deprivation therapies (ADT), which inhibit the transcriptional activity of the androgen receptor (AR)." (PMID 37663929, 2023). "We have used both subcutaneous cell-derived xenograft models (DU-145 and PC3 prostate cancer cells engrafted in NSG mice) and AR-positive/PSA-expressing prostate cancer PDX model (TM00298 PDX tumors engrafted in NSG mice) as in vivo models." (PMID 36765659, 2023). "MAPK4 also enhances AR function via the stimulation of GATA2 gene expression and protein stability, thus leading to increased prostate cancer cell proliferation." (PMID 36768610, 2023). "Aberrant Androgen receptor (AR) and PI3K‐AKT signaling are very frequent in prostate cancer (PCa) patients." (PMID 37877351, 2023). "However, reports that decreased HECTD4 in prostate cancer leads to increased AR and MYC proteins and that increased AR/MYC is oncogenic in OSCC suggest that loss‐of‐function mutations in HECTD4 are oncogenic and may be a cause of carcinogenesis in elderly nonsmokers." (PMID 37272305, 2023). "By focusing on specific genes of interest, such as AR, PTEN, and ERG, known to impact prostate cancer progression and metastasis, we discovered novel regulatory interactions." (PMID 37686146, 2023). "The SMAD3 peak in AR intron 3 overlapped with H3K27ac ChIP-seq and ATAC-seq peaks in datasets of prostate cancer." (PMID 36727462, 2023). "To determine if RIOX2 expression was directly regulated by the androgen/AR signal pathway, we analyzed RIOX2 expression in prostate cancer LNCaP cells after androgen stimulation." (PMID 36776320, 2023). "Therapeutic approaches directed toward a single pathway or single target such as AR antagonism or prostate-specific membrane antigen radioligand therapy may potently inhibit specific disease subtypes but are unlikely to overcome the heterogeneity commonly seen in advanced prostate cancer." (PMID 37823778, 2023). "We further found that testosterone promoted AR and FEN1 expression in prostate cancer cells, while DTX treatment yielded the opposite results." (PMID 37326412, 2023). "Most prostate cancers are adenocarcinomas, initially being hormone-sensitive prostate cancer (HSPC) with the expression of androgen receptor (AR) and prostate-specific antigen (PSA)." (PMID 37240468, 2023). "KLF9 is a potent growth suppressor in prostate cancer cell lines in vitro and this involves, in part, the repression of two major pathways, namely those for AKT and the androgen receptor (AR), along with the induction of apoptosis." (PMID 38067370, 2023). "AR and SMAD3 mRNAs were upregulated in datasets of metastatic prostate cancer and CRPC compared with primary prostate cancer." (PMID 36727462, 2023). "Using targeted multiplexed proteomics, we detected varying expression levels of the tissue of origin markers such as ER and HER2 in the breast cancer cases, or AR, PSA, and PSMA in prostate cancer cases." (PMID 37568766, 2023).
prostate carcinoma (continued). "USP22 positively regulates c-Myc, androgen receptor, and HIF-1α actions to promote breast cancer, prostate cancer, and HCC progression." (PMID 36906615, 2023). "It is an androgen-driven disease with signaling through the androgen receptor (AR), and although androgen deprivation therapy (ADT) can control tumor growth, many patients go on to develop castrate-resistant prostate cancer." (PMID 37628903, 2023). "AR inhibition enhanced the expression of NK1R, which mediated the PKCα-AURKA/N-Myc pathway in prostate cancer cells." (PMID 37385990, 2023). "Multiple molecular signaling targets, including androgen receptor (AR) and others, play an important role in the development and progression of CRPC and other advanced prostate cancers." (PMID 36709328, 2023). "Comparing the DNA methylation and expression profile of androgen-sensitive and -refractory prostate cancer cells, we describe the epigenetic silencing of claudin-3 (CLDN3) in AR positive cells resistant to androgen deprivation (LNCaP-abl)." (PMID 36614243, 2023). "In prostate cancer, inhibition of NMT1 also blocks the scaffold function of Src kinase and prevents protein–protein interaction with the androgen receptor (AR), thus inhibiting androgen-independent AR activation." (PMID 37140999, 2023). "In prostate cancer, overexpression of HECTD4 has been reported to result in a simultaneous decrease in both androgen receptor (AR) and MYC proteins, while knockdown of HECTD4 results in an increase in both AR and MYC proteins." (PMID 37272305, 2023). "Similar results have been reported for the relationship between AR and ACSL4 expression in prostate cancer." (PMID 37306503, 2023). "We previously showed that expression of GALNT7 is controlled by the AR and that GALNT7 is upregulated in prostate cancer cells in response to androgen stimulation." (PMID 36725887, 2023). "In prostate cancer (PCa) cells, the expression of the TRPM8 channel is controlled by androgens via androgen receptor (AR) activation." (PMID 37033630, 2023). "Specifically in prostate cancers, ORC participates the androgen receptor (AR) regulated genomic amplification and tumor proliferation throughout the entire cell cycle." (PMID 36978046, 2023). "Another inhibitor, CCS1477, inhibits prostate cancer cell proliferation and reduces the expression of AR and c-MYC regulatory genes, making it a promising novel prostate cancer treatment." (PMID 36979352, 2023). "Therapeutic strategies for castration-resistant prostate cancer are limited, and the emergence of neuroendocrine differentiation in CRPC patients as a result of treatment with second generation of AR pathway inhibitors poses significant clinical challenges." (PMID 38201476, 2023). "It shares an implication in prostate cancer with ETV5, AR and ERG; while ACE2 shares its importance in the development of COVID-19." (PMID 37287057, 2023). "Some of these proteins including AR, SMAD, NANOG, EZH2, and KLF have demonstrated prognostic significance in advance-stage prostate cancer." (PMID 36672280, 2023). "Androgen receptor (AR) signaling plays a key role in development of Benign prostatic hyperplasia (BPH) and prostate cancer." (PMID 37860121, 2023). "To this end, we employed specific inhibitors to TBK1 (GSK8612; GSK) and JAK1/2 (Ruxolitnib; Ruxo) in prostate cancer cell lines and induced PARP7 via AHR (PC3, DU145) and AR (PC3-AR)." (PMID 37077937, 2023). "The first generation of AR inhibitors approved by the American Food and Drug Administration (FDA) for prostate cancer treatment included bicalutamide, flutamide, and nilutamide, which were launched between 1989 and 1996." (PMID 36768610, 2023).
prostate carcinoma (continued). "In contrast, expressions of the AR and VDR were unchanged between EA and AA prostate cancer samples." (PMID 37082578, 2023). "However, in AR-v7 variants, the abundance of AR-rich condensates is diminished due to loss of the interaction between the ligand-binding domain and activation function 1 (AF1) of AR, resulting in impaired regulation of AR's transcriptional role in prostate cancer." (PMID 37705755, 2023). "To investigate the biochemical and biological consequences of EZH2 and HDAC inhibitors in prostate cancer, we used a panel of cell lines including PC3 (AR-), C42B (AR independent), LnCAP (AR dependent), and PT-09 cells (mouse, AR independent)." (PMID 37104245, 2023). "On the other hand, methylation of the androgen receptor augmented its transcriptional functions and, accordingly, SET7/9 supported growth and survival of androgen-dependent prostate cancer cells." (PMID 37870957, 2023). "Treatment with AU-15330 induced selective proteolysis of the core subunits (SMARCA2 and SMARCA4) and promoted the dislodging of AR and FOXA1 from chromatin in prostate cancer cell lines and suppressed the growth of xenograft prostatic tumors in mice." (PMID 37025180, 2023). "In prostate cancer, ATIRE alters the interaction of androgen receptor with androgens or anti-androgenic ligands." (PMID 36999050, 2023). "GATA2 is a critical pioneer TF for AR, trans-activated IGF2 to mediate taxane resistance in prostate cancer or promote chemoresistance in gastric cancer via the EGFR signalling pathway." (PMID 38126976, 2023). "We thus expected that AR and MYC would have convergent signaling in prostate cancer and mCRPC, but to lesser degrees in normal prostate tissue." (PMID 37059746, 2023). "Although AR transcriptional activity can be restored in CRPC, a mouse study found that long-term androgen deprivation in prostate cancer tumors responds to androgens and leads to slower tumor progression." (PMID 37142586, 2023). "Due to the fact that the binding of androgen to AR initiates the transcriptional pathway, androgen deprivation therapy (ADT) has been a mainstay of treatments for prostate cancer since 1941." (PMID 37444418, 2023). "In prostate cancer, the majority of DNA vaccines have targeted specific antigens such as PAP, PSA, or androgen receptor." (PMID 37762648, 2023). "The androgen receptor (AR, NR3C4) is the key driver of prostate cancer (PCa) initiation and progression." (PMID 37152294, 2023). "For example, in prostate cancer cells, LSD2 and FHL2 can specifically bind to androgen receptor (AR) to activate the expression of androgen related target genes." (PMID 37207209, 2023). "Androgen receptor signaling drives prostate cancer growth, and a mainstay of treatment for prostate cancer is androgen deprivation therapy (ADT) which interrupts the androgen receptor signaling cascade." (PMID 36998466, 2023). "In prostate cancer, oncogenic alterations in PIK3CA and AR were enriched in TMB and bTMB≥10 samples, whereas TMPRSS2-ERG fusions were more likely to be found in TMB and bTMB<10 samples." (PMID 40027285, 2023). "Direct antagonism between AR and WNT/β-catenin signaling has been suggested before for epidermal stem cells and prostate cancer cells." (PMID 37102205, 2023). "This study confirmed the potential linkages between androgen and NF-κB activation by inducing MALT1 in the androgen receptor-full length (ARFL)-positive LNCaP and 22Rv1 prostate cancer cells." (PMID 37047218, 2023). "We characterized the effect of RBN2397 in prostate cancer cells, first by examining its ability to inhibit PARP7 ADP-ribosylation of AR." (PMID 37077937, 2023). "In contrast to the role of integrin αvβ6 in prostate cancer, integrin α6β1 is involved in the survival of castration-resistant prostate cancer (CRPC) cells in response to AR signaling." (PMID 37681860, 2023). "In prostate cancer, PTGES3 was reported to induce the androgen receptor activity and chromatin binding to promote tumorigenesis." (PMID 37416927, 2023).
prostate carcinoma (continued). "In prostate cancer, AKR1C3 is upregulated by androgen-deprivation therapy, which confers resistance to androgen receptor (AR) antagonists, such as enzalutamide." (PMID 38188684, 2023). "Additional studies expand on a role for ACSL4 in promoting prostate cancer growth, invasion and hormone resistance, confirming an inverse relationship between ACSL4 expression and that of the androgen receptor." (PMID 37306503, 2023). "For advanced prostate cancer, androgen deprivation therapy (ADT) is the primary and initially effective treatment due to that prostate cancer is driven by androgens and the androgen receptor (AR)." (PMID 37591798, 2023). "We determined that RBN2397 inhibits the growth of prostate cancer cells dependent on transcriptional induction of PARP7, achievable by treating cells with androgen to activate AR, or with ligands that activate AHR." (PMID 37077937, 2023). "In contrast, late PCCs lost expression of epithelial markers, although PCCs prepared from PCaT continued to express androgen receptor (AR1) and prostate cancer markers AMACR and EZH2." (PMID 36769153, 2023). "Looking at the literature, AR signaling and PI3K-AKT signaling have cross-dialogue, which jointly regulate the proliferation of androgen-dependent prostate cancer cells." (PMID 37567936, 2023). "These metabolites inhibited key proteins of DU-145 prostate cancer using molecular docking with rutin owning the highest binding affinity with PIKR31 and AR." (PMID 37687413, 2023). "In this study, we demonstrate the potential role of VNPP433-3β as molecular glue that induces physical proximity between the Androgen Receptor and MDM2 E3 ligase in prostate cancer cells." (PMID 36831540, 2023). "LSD1 was initially reported to act as an AR co-activator via demethylation of methylated H3K9 residue, along with upregulated expression of LSD1 in malignant prostate tumors." (PMID 37025180, 2023). "The clinical relevance of such strategy is huge since targeting both AR-positive and AR-negative prostate cancer cell populations would provide a two-pronged approach to eliminate CRPC cells, irrespectively of AR status." (PMID 35740556, 2022). "In many cases, such as for AR, MYC, and FOXA1, these hotspots overlap with active chromatin marks and likely represent distal regulatory regions for neighboring prostate cancer genes, as shown by our analyses overlapping SVs with ChIP-Seq on mCRPC specimens." (PMID 35943799, 2022). "Of note, in prostate cancer, which is also dependent on AR and PI3K signaling, it has been shown that inhibition of the PI3K pathway activates AR signaling to support tumor survival." (PMID 35774123, 2022). "Recently, we investigated the role of androgen-dependent mitochondrial fission on prostate cancer cell survival and found that DRP1 is upregulated by androgen receptor (AR) signaling." (PMID 35269393, 2022). "To provide additional evidence for the existence of AR and NE double-positive cells, we performed multiplex fluorescence staining and observed the co-localization of AR and SYP in the same prostate cancer cells." (PMID 36033483, 2022). "For example, it has recently been shown that androgen receptor (AR) and forkhead box A1 (FOXA1) expressing prostate cancer cells are sensitive to simultaneous degradation of BAF complex subunits SMARCA2, SMARCA4 and PBRM131." (PMID 36216795, 2022). "However, in about 20% of prostate cancers, these treatments may trigger differentiation of adeno-CRPC towards aggressive anaplastic and neuroendocrine tumors that are associated with loss of canonical AR activity." (PMID 35963852, 2022). "Another study showed that the progression of prostate cancer in the xenograft model was inhibited by triptolide via limited SUMO-specific protease 1 activity (SENP1), as well as androgen receptor expression and c-Jun transcription activity." (PMID 35267408, 2022).
prostate carcinoma (continued). "To address this question, we performed immunohistochemistry staining of AR, PSA, and different NE markers in serial pathological sections of 189 prostate cancer patients with neuroendocrine differentiation." (PMID 36033483, 2022). "As an inhibitor of androgen receptor (AR), EPI-001 is being explored for the treatment of prostate cancer." (PMID 36555703, 2022). "The mechanism of reduced cell growth is due to the repression of AR/PSA survival signaling, which is vital in promoting prostate cancer." (PMID 35630591, 2022). "ARD-69 showed effective AR degradation activity in LNCaP (DC50 = 0.86 nM), VCap (DC50 = 0.76 nM), and 22Rv1 prostate cancer cell lines and in a VCaP xenograft mouse model." (PMID 36235052, 2022). "The combination of metformin and the antiandrogen bicalutamide synergistically decreased the growth of AR-positive LNCaP cells, LAPC4 cells, and PDX models of prostate cancer." (PMID 36175875, 2022). "In prostate cancer, PTN regulates mesenchymal and epithelial proliferation, with PTN itself being regulated by the androgen receptor during prostate development." (PMID 35365620, 2022). "The expressions of AR, MYC and FOXA1 genes themselves are frequently amplified in advanced prostate cancer by copy amplification and/or enhancer duplication." (PMID 34937944, 2022). "In mouse models of prostate cancer, AR inhibition led to activation of the PARP pathway, and dual inhibition of AR and PARP led to synthetic lethality." (PMID 35163621, 2022). "In this regard, studies have investigated the effect of SIRT1 expression on AR, as a mechanism of SIRT1 in the development and progression of prostate cancer." (PMID 36291902, 2022). "Further, AR blockade combined with androgen deprivation therapy (ADT) increased the T cell response to PD1 inhibition and prolonged survival in mouse models of prostate cancer and sarcoma." (PMID 36337733, 2022). "In androgen-sensitive prostate cancer cells, SFRP1 has been shown to inhibit AR transcriptional activity independently of Wnt/β-catenin signaling." (PMID 35204808, 2022). "The obtained Au‐AR pep‐PROTAC effectively degrades AR and AR‐V7 in prostate cancer cell lines, particularly in CWR22Rv1 cells with DC50 values 48.8 and 79.2 nM, respectively." (PMID 35971165, 2022). "In this study, we demonstrate that VNPP433-3β physically interacts with AR LBD in vitro and directly engages fAR within the live prostate cancer cells." (PMID 36078112, 2022). "Despite that previous studies have demonstrated the pioneer functionality of GATA2 in hormone-induced prostate cancer cells, all of these studies emphasized on the pioneering role of GATA2 in activating or enhancing AR-dependent gene transcription." (PMID 35672415, 2022). "In castration-resistant prostate cancer cells, combining androgen receptor (AR) antagonist with ACLY inhibition promoted AMPK activation and lead to suppression of AR levels to induce apoptosis." (PMID 35646898, 2022). "In prostate cancer, CBX3 has been demonstrated to regulate androgen receptor signaling and upregulate c-Myc to promote tumor progression." (PMID 34785774, 2022). "An inverse relationship between androgen receptor and WT1 expression has been found in prostate cancer cell lines, together with WT1 repression of the androgen receptor promoter." (PMID 37733393, 2022). "Preclinical studies of prostate cancer demonstrate that PARP1 enzymatic activity is enhanced and required for AR function, tumour cell growth, and progression to castration resistance." (PMID 36497408, 2022).